INS (insulin)
Diseases named in the same sentence as INS in open-access papers (continued):
Sharing a sentence is not in itself a finding about the gene and the disease.
type 2 diabetes (continued). "Physical exercise improves insulin sensitivity and whole body metabolism and remains one of the most promising interventions for the prevention of Type 2 diabetes." (PMID 28248217, 2016). "Taken together, these studies both provide evidence for a sexually dichotomous role of insulin in the development of type-2 diabetes." (PMID 26823968, 2016). "These pathways are insulin signaling pathway, insulin resistance, glucagon signaling pathway, type II diabetes mellitus, AMPK signaling pathway, PPAR signaling pathway, and malaria." (PMID 28224024, 2016). "All patients with type 1 diabetes and a significant number with type 2 diabetes require the use of insulin for controlling blood glucose." (PMID 26742082, 2016). "Growing evidence has suggested that oxidative stress plays an important role in the pathogenesis of type 2 diabetes (T2D) by promoting insulin resistance or impairing insulin secretion." (PMID 27685994, 2016). "In conclusion, basal insulin requirement is 40% TDD in newly diagnosed patients with type 2 diabetes in China." (PMID 26697503, 2016). "Overall, 57 (95 %) patients had type 2 diabetes of whom 24 (42 %) were insulin-dependent prior to ICU admission." (PMID 27633987, 2016). "Protein tyrosine phosphatase 1B (PTP1B), a negative regulator of insulin signaling, has become the intense pharmaceutical interest for treating type-2 diabetes over the past decade." (PMID 26808535, 2016). "A clinical trial on the efficacy of INT-747 demonstrated that this compound is able to enhance insulin sensitivity in type 2 diabetics." (PMID 26770984, 2016). "Rosiglitazone is a well-known PPARγ agonist that increases peripheral INS sensitivity and improves glycaemic control in type 2 diabetes." (PMID 27638500, 2016). "Elevations in serum proinsulin/insulin ratio have been shown in patients with type 2 diabetes and those with new onset type 1 diabetes, while improvement in this ratio was reported following treatment with pioglitazone and IL-1β receptor antagonist therapy." (PMID 26840310, 2016). "The current study aimed to characterize the real-world insulin treatment patterns and associated utilization of healthcare services among patients with type 2 diabetes who initiated insulin therapy during the study period." (PMID 26759271, 2016). "Sulfonylureas are often used as a first-line treatment in type 2 diabetes, as they increase insulin release from beta cells." (PMID 27033560, 2016). "Increased ectopic fat depot, typically abdominal VAT, is strongly related to insulin resistance, producing inflammatory cytokines, and the development of type II diabetes mellitus." (PMID 26904670, 2016). "The top behaviour relevant to people with Type 1 diabetes was ‘taking insulin as required’ and for people with Type 2 diabetes was ‘attending and engaging with structured education programmes’." (PMID 29062515, 2016). "Insulin secretagogues including sulfonylureas, glinides, and incretin-related drugs are widely used in clinical practice for treatment of patients with type 2 diabetes with impaired insulin secretion." (PMID 27764176, 2016). "In conclusion, we demonstrated that the FINDRISC is a simple tool for the detection of early adverse changes in insulin secretion and insulin sensitivity which likely explain the conversion to type 2 diabetes." (PMID 27851812, 2016). "The UK guidelines use age at diagnosis and time to insulin as the classification criteria to differentiate between type 1 and type 2 diabetes." (PMID 27080317, 2016). "In type 2 diabetes, insulin resistance of peripheral tissues can lead to chronically high blood sugar levels, placing an inordinate demand on β cells for insulin supply, eventually overwhelming the capacity of β cells to respond." (PMID 27600088, 2016). "Collectively, pancreatic β-cell dysfunction and reduced insulin secretion play an important role in the pathogenesis of both type 1 and type 2 diabetes." (PMID 26779540, 2016).
type 2 diabetes (continued). "The patient was diagnosed with type 2 diabetes as serum insulin level (3.4 μU/ml) and urinary C-peptide response (>200 μg/day) were preserved and autoantibodies related to type 1 diabetes were absent." (PMID 27652072, 2016). "The most common reasons for ineligibility included being too physically active (11 %), currently taking vitamin D supplements at a dose of >500 IU/day (11 %) and management of type 2 diabetes by way of insulin therapy (5 %)." (PMID 27669823, 2016). "In Canada, the annual cost of insulin- and sulfonylurea-induced hypoglycemia in older type 2 diabetic adults attaining very tight glycemic control was estimated to be CAN$29,913,883 and CAN$35,583,966, respectively, for a combined cost of CAN$65,497,849." (PMID 27648831, 2016). "Thiazolidinedione drugs, such as RGZ or pioglitazone, agonists of PPARγ, are used to treat type 2 diabetes by improving insulin sensitivity." (PMID 28066247, 2016). "Regarding type 2 diabetes, because of the pancreatic β-cells’ imperfection, damage or insulin resistance, the total secretion of insulin is insufficient, and as a result, the blood glucose of diabetics is much higher than the ordinary level." (PMID 27754463, 2016). "The most serious adverse effect of insulin therapy is hypoglycemia, but the frequency and severity of this effect is less in type 2 diabetes than in type 1 diabetes." (PMID 27278922, 2016). "This study has shown that the UK guidelines based on time to insulin and age at diagnosis are accurate and pragmatic for classifying patients with type 1 or type 2 diabetes." (PMID 27080317, 2016). "This clinical, prospective, randomized, crossover study compared the effects of two different classes of drugs (rosiglitazone, an insulin sensitizer, and nateglinide, an insulin secretagogue) in type 2 diabetes patient." (PMID 26734075, 2016). "Type II diabetes is characterized through decreased insulin secretion, long-term high blood glucose and increased glucagon release." (PMID 27013590, 2016). "The phase II clinical trials data showed that INCB-13739 significantly improved insulin sensitivity in type 2 diabetic patients who failed in metformin treatment, and reduced the levels of triglyceride and cholesterol in hyperlipidemic patients." (PMID 27657020, 2016). "Insulin secretion and action are the main determinants of type 2 diabetes, although with varying quantitative contributions in different ethnic populations." (PMID 27938404, 2016). "The results showed that endogenous insulin/IGF-1 accelerates colon tumor growth in a mouse type 2 diabetes model." (PMID 26901856, 2016). "Mitochondrial dysfunction and reduced insulin secretion are key features of β-cell dysfunction in Type 2 diabetes (T2D)." (PMID 27195491, 2016). "Impairments in insulin action in skeletal muscle have been clearly established as one of the early and primary defects in the pathogenesis of Type 2 diabetes." (PMID 28248217, 2016). "The main regulatory hormone involved in metabolism is insulin, and hence, insulin-resistant states such as obesity and type 2 diabetes are characterised by a reduction in metabolic flexibility." (PMID 27306890, 2016). "Type 2 diabetes mellitus (T2DM) is caused by β-cell dysfunction and the deterioration of glycemic control, as well as impaired insulin secretion and sensitivity." (PMID 27854254, 2016). "Our aim is to compare the effectiveness of the addition of metformin to insulin, to standard care (insulin plus placebo) in women with type 2 diabetes in pregnancy." (PMID 27435163, 2016). "MSCs and MSC-conditioned medium (MSC-CM) as renal trophic factors were administered in parallel to high-fat diet (HFD)-induced type 2 diabetic mice and streptozotocin (STZ)-induced insulin-deficient diabetic mice." (PMID 27721418, 2016). "Inflammatory cytokines, including IL-1β, inhibit insulin-dependent glucose uptake and are increasingly recognized to play an important role in insulin-resistance in the pathogenesis of type 2 diabetes." (PMID 27438413, 2016).
type 2 diabetes (continued). "Consumption of red grape extract improved fructose-induced ER-stress and insulin sensitivity in healthy, overweight first-degree relatives of patients with type 2 diabetes." (PMID 27977712, 2016). "Type 2 diabetes (T2D) is a progressive chronic disease, primarily characterized by functional decline of beta cell, worsening of insulin signaling, and muscle atrophy." (PMID 27512375, 2016). "It seems that the onset of type 2 diabetes or other clinical complications are a consequence of the increase in the number of organs with reduced insulin sensitivity." (PMID 28933394, 2016). "The inclusion of populations who are insulin resistant, have type 2 diabetes, and/or exhibit a greater range of vitamin D status would allow for greater exploration of the relationship between vitamin D status, and insulin sensitivity and protein signaling." (PMID 27754361, 2016). "Following the treatment, researchers observed a dysregulation of type 2 diabetes and insulin signaling pathways in the hypothalamus." (PMID 27231920, 2016). "Insulin‐sensitive or metabolically healthy individuals with obesity are suggested to be relatively protected from type 2 diabetes in longitudinal studies." (PMID 26916476, 2016). "Under pathophysiological conditions like type 2 diabetes, insulin resistance of adipose tissue results in disinhibition of adipose tissue lipolysis by insulin." (PMID 26864436, 2016). "The next steps should include an in-depth exploration of the CB1-mTORC1 interaction in the modulation of both glucose-stimulated insulin secretion and β-cell mass expansion both in human islets and in animal models of type 2 diabetes." (PMID 26563389, 2016). "There is compelling evidence that genetic factors affecting insulin secretion contribute to the pathogenesis of type 2 diabetes." (PMID 27685945, 2016). "A recent study demonstrated an immediate and highly repetitive deterioration of cardiac function after a carbohydrate meal associated with increased oxidative stress in overweight and insulin-dependent patients with type 2 diabetes." (PMID 26772807, 2016). "Fourthly, the number of patients with Type 1 diabetes in this series is very low, even though a significant number of patients were classified as insulin-requiring Type 2 diabetes patients." (PMID 27907053, 2016). "Type 2 diabetes is characterized by impaired insulin secretion from pancreatic β-cells and impaired insulin sensitivity in target tissues including liver, adipose tissues, and muscles." (PMID 27764176, 2016). "In the last thirty years, MI and DCI attracted a growing interest since the discovery of their role in insulin-activated signaling pathways and in the physiopathology of metabolic syndrome and type II diabetes." (PMID 27579037, 2016). "Type II diabetes (T2D) is considered as the heterogeneous disease with altered insulin production by the pancreatic beta cell." (PMID 27350825, 2016). "MRI studies of the pancreas were carried out, allowing us to report for the first time on the effect on pancreas morphology of the duration of type 2 diabetes and of sustained restoration of insulin secretory function." (PMID 27179658, 2016). "In people with type 2 diabetes (the most common typeof diabetes), blood sugar control fails because the fat and muscle cellsthat normally respond to insulin by removing excess sugar from the bloodbecome resistant to insulin." (PMID 27071029, 2016). "Defects in insulin secretion occur early in the pathogenesis of type 2 diabetes, and both reduction in β-cell mass and intrinsic β-cell dysfunction contribute to the defective insulin secretion in type 2 diabetes." (PMID 27685945, 2016). "A potential weakness, however, is that the MDKT does not include questions related to specific new treatment regimens such as insulin pump treatment or various types of glucose-lowering medications for type 2 diabetes." (PMID 27366112, 2016).
type 2 diabetes (continued). "In the mouse model of type 2 diabetes, thyroid hormone has been shown to improve glycaemia and insulin sensitivity." (PMID 26586839, 2016). "GPR142 is an islet-enriched G protein-coupled receptor that has been investigated as a novel therapeutic target for the treatment of type 2 diabetes by virtue of its insulin secretagogue activity." (PMID 27104960, 2016). "The centre’s typical patient composition comprises up to 60% of patients with type 1 diabetes, and the majority of patients with type 2 diabetes is treated with insulin; both patient groups typically live with the condition for many years." (PMID 26938980, 2016). "We examined the real-world utilization and persistence of rapid acting insulin (RAI) in elderly patients with type 2 diabetes who added RAI to their drug (OAD) regimen." (PMID 27761472, 2016). "The MiTy trial is a multi-centre randomized trial currently enrolling pregnant women with type 2 diabetes, who are on insulin, between the ages of 18–45, with a gestational age of 6 weeks 0 days to 22 weeks 6 days." (PMID 27435163, 2016). "Pancreatic β-cells synthesize and secrete insulin for glucose homeostasis, and decrease in the number of functional β-cells results in type 1 and type 2 diabetes." (PMID 27000077, 2016). "In conclusion, we were able to reduce the bolus insulin dose and further improve postprandial blood glucose and HbA1c levels by adding vildagliptin to the treatment regimens of patients with type 2 diabetes receiving insulin." (PMID 25780477, 2015). "Humpert and coworkers have demonstrated that insulin stimulates the outgrowth in vitro of EPCs from patients with type 2 diabetes." (PMID 26089898, 2015). "Both l-glutamine and whole protein restored first-phase insulin response in type 2 diabetes patients." (PMID 25811109, 2015). "It has been shown previously that pioglitazone enhances both hepatic and peripheral insulin sensitivity in both type 2 diabetic patients and patients with IGT." (PMID 25954816, 2015). "In this study, the short-term use of liraglutide enhanced insulin sensitivity in patients with type 2 diabetes." (PMID 25922845, 2015). "Insulin resistance (IR) is defined as the inability of target tissues to increase glucose uptake in response to insulin, which eventually leads to type II diabetes mellitus (T2DM)." (PMID 26942223, 2015). "Larger studies are required to further investigate the utility of similar approaches in improving insulin secretory capacity in type 2 diabetes." (PMID 25811109, 2015). "In an older, mainly white veteran population with type 2 diabetes, conversion from insulin glargine to insulin detemir resulted in an increase in A1c post-conversion, decrease in weight and BMI, and an increase in total daily dose." (PMID 26120575, 2015). "A popular option in type 2 diabetes is to use a ‘premixed’ insulin formulation whereby a single injection can be given with main meals to supplement both prandial and basal insulin output." (PMID 25563978, 2015). "Sitagliptin has been demonstrated to improve glycemic control when added to SUs, metformin, pioglitazone, and insulin therapy in Japanese patients with type 2 diabetes." (PMID 25699116, 2015). "Low concentrations of adiponectin, the most abundant adipose-specific protein, occur in obesity and predict both a decrease in insulin sensitivity and development of type 2 diabetes mellitus (T2DM)." (PMID 26110385, 2015). "Enlarged subcutaneous adipocytes have been shown to predict type 2 diabetes in a prospective cohort, independent from clamp-measured insulin sensitivity." (PMID 25771885, 2015). "During the development of type 2 diabetes, endoplasmic reticulum (ER) stress leads to not only insulin resistance but also to pancreatic beta cell failure." (PMID 26091000, 2015). "Some research also links PCBs to increased rates of type 2 diabetes from decreased insulin sensitivity in peripheral tissues." (PMID 26086818, 2015).
type 2 diabetes (continued). "The effect was mostly driven by myocardial infarction end point, supporting the concept of macrovascular benefit for basal analogue insulin use in type 2 diabetes." (PMID 26176017, 2015). "Excessive lipid storage can induce insulin resistance of skeletal muscle, and under severe conditions, lead to type 2 diabetes." (PMID 26942218, 2015). "DPP4 is thought to play a role in glucose homeostasis and type-2 diabetes by inactivating incretin hormones involved in glucose-dependent insulin secretion." (PMID 25651499, 2015). "The aim of this study was therefore to examine health care utilization and costs in our recent study with 5,077 insulin-naïve type 2 diabetes patients, after starting treatment with NPH, IG, ID or PM." (PMID 28702235, 2015). "Concerning treatment of hyperglycemia, insulin treatment was more frequent in LADA than in type 2 diabetes (62.5% vs. 26.7; p = 0.005)." (PMID 25572256, 2015). "Type 2 diabetes is characterized by insulin resistance and abnormal insulin secretion and accounts for 85–95 % of diabetes cases globally [4•]." (PMID 25903071, 2015). "Type 2 diabetes mellitus (T2DM) is characterized because pancreatic β cells cannot synthesize adequate amounts of insulin to satisfy the metabolic demand of peripheral tissues such as skeletal muscle, adipose tissue, and liver." (PMID 26366171, 2015). "Taken together, these results suggest that IN delivery of GNP holds promise as a future rescue medication for use by caregivers to treat insulin-induced hypoglycemic episodes in patients with type 1 or type 2 diabetes." (PMID 26502880, 2015). "Type 2 diabetes (T2D) can be defined as a bihormonal metabolic disorder characterised by insufficient insulin secretion and abnormal glucagon secretion." (PMID 26258597, 2015). "In patients with type-2 diabetes receiving oral antidiabetic drugs (OADs), the addition of insulin is frequently required to achieve sufficient control over blood glucose levels." (PMID 26446863, 2015). "In conclusion, in patients with obesity and type 2 diabetes, insulin infusion leads to a suppression of the expression of IL-4, ADAM-33, LIGHT, and LTBR in parallel with a reduction in plasma NOM, TGFβ, MCP-1, and MMP-9 concentrations." (PMID 25642424, 2015). "In obesity and type 2 diabetes a decrease in insulin-stimulated glucose transport is observed; in addition, alterations on metabolism of adipocytes, skeletal muscle, and hepatic glucose output are also reported (Reaven, 1995)." (PMID 26869866, 2015). "For minor outpatient surgeries, type 1 or type 2 diabetes can be managed by IV infusion or subcutaneous insulin strategies." (PMID 26078998, 2015). "Many of the patients with type 2 diabetes were taking insulin one or more times a day, as was the individual with type 1 diabetes." (PMID 26290186, 2015). "Although controversial effects on insulin secretion in vitro were reported, berberine lowered hyperglycemia, improved insulin resistance, and stimulated pancreatic beta cell regeneration in type 2 diabetic animals." (PMID 26587047, 2015). "Several specific molecular targets in the insulin signaling pathway have been considered as novel therapeutic approaches for type 2 diabetes." (PMID 26193288, 2015). "In the long-standing type 2 diabetes, C-peptide level is also decreasing over time and these patients need insulin therapy but the variations of their glucose level are less than type 1 diabetes due to the insulin resistance." (PMID 25621692, 2015). "The present study investigates the effects of vinegar on circulating plasma glucose, insulin, and lipid levels, as well as blood flow rates and glucose uptake by the forearm muscles, in patients with type 2 diabetes." (PMID 26064976, 2015). "The insulin resistant proinflammatory states of obesity and type 2 diabetes are characterized by an increase in IL-4, MMP-9, LIGHT, and CCR-2 expression in MNC and MMP-9 and NOM concentrations in plasma." (PMID 25642424, 2015).